IL2 (interleukin 2)
Diseases named in the same sentence as IL2 in open-access papers (continued):
Sharing a sentence is not in itself a finding about the gene and the disease.
influenza (continued). "Interestingly, and in contrast with the response to pertussis, IgG depletion enhanced IFN-γ production in response to H1N1, and IL-2 blockade slightly decreased degranulation, indicating competition between these pathways for NK cell activation during influenza responses." (PMID 25855356, 2015). "Thus expression of IL-2 in the anti-influenza response may be regulated mainly by short term variability, whereas different T cell subsets, Th1 and Thpp, may contribute to variability in IFNγ expression." (PMID 24788814, 2014). "In comparison to influenza and bacterial CAP, patients with AdV had higher serum IL-2, IL-1β, IL-8, IL-10, CXCL10 and MCP-1, and lower TGF-β1 concentration." (PMID 39858309, 2025). "Upon re-exposure to influenza antigens, these memory subsets promptly recognize viral peptides presented by local APCs and produce cytokines such as IFN-γ, TNF-α, and IL-2 within hours." (PMID 40872830, 2025). "When comparing major trends between cytokeratins, CK8/18 and CK19 were the most similar, including the production of the anti-inflammatory cytokines IL-2, IL-9, IL-10, and TNF-β among influenza-infected (CK+FLU+ ) populations." (PMID 39791909, 2025). "The IL-2 dynamics in asthma and COPD patients vaccinated against influenza and healthy volunteers (reference value: Less than 10 pg/mL)." (PMID 39937802, 2025). "The results in mouse cells, including influenza infection and T cell–induced colitis models, as well as in primary human cells, indicate that BLIMP1 negatively regulates IL-2 signaling that helps to modulate the immune response." (PMID 40680114, 2025). "Immunokinetic patterns were pathogen-specific, including transient increase in IL-17A and IL-10 in Legionella and Mycoplasma infections, and CXCL10, IL-2, IL-17A, TGF-β1 and IL-10 in influenza." (PMID 40869413, 2025). "The number of influenza-specific CD4+ polypositive T cells, defined as CD4+ T cells producing at least two of the following immune markers: CD40L, IFNγ, IL-2, and TNFα, exhibited similar trends between cohorts at any visit for any vaccine strain." (PMID 39340066, 2024). "Among the influenza HAs, A/H3-specific IFN-γ and IL-2 secreting cells reached the highest level, while those specific to B/Victoria reached the lowest level." (PMID 39105586, 2024). "Influenza-infection-induced Th1 effector cells express antiviral cytokines, such as IFN-γ, TNFα, and IL-2, and activate alveolar macrophages." (PMID 39066362, 2024). "Following the transfer of antigen-primed T cells into influenza-infected mice, IL-2 neutralization greatly decreases CD4+ TRM cell formation, and a residual memory population is maintained independently of IL-2 signaling." (PMID 37545498, 2023). "Another research paper showed that Se-deficiency increased the mRNA level of cytokines like IL-4, IL-5, IL-10 and IL-13, whereas it decreased the level of IL-2 and interferon-γ (IFN-γ) in influenza-infected mice." (PMID 36837803, 2023). "Treg consumption of IL-2 has also been demonstrated to promote induction of TFH in an influenza mouse model as well as TH17 cells, both of which mature in the context of low concentrations of IL-2." (PMID 36420277, 2022). "In a mouse model of influenza infection, germinal center TFH were found to be unresponsive to IL-2 through an IL-6 dependent mechanism." (PMID 36420277, 2022). "MC-derived cytokines of potential interest in suppressing influenza immunopathology include: TNFα, TGF-β1, GM-CSF, IL-2, IL-9, IL-13, and IL-33." (PMID 33680987, 2021). "In contrast, levels of IL-1RA, IL-2, TNF-α, CCL3, and G-CSF were more increased among pandemic influenza A(H1N1) patients." (PMID 33995342, 2021). "T-cell responses were assessed by analysing the frequencies of influenza-specific CD4+ and CD8+ T producing IFN-γ, IL-2, and TNF-α in PBMC harvested on days 1 and 22 from participants in groups MAP-FA-0, MAP-FA-15, MAP-UA-15, and IM-QIV-15." (PMID 32181756, 2020).
influenza (continued). "Culturing B cells in the presence of anti-CD40, IL-4 and IL-21 was found to trigger influenza antigen-specific ASC in frequencies similar to R848 and IL-2 stimulation." (PMID 32069813, 2020). "After influenza infection, IFN-α/β, IFN-α, and IL-2 appear to have protective roles against influenza infection, while IL-1, TNF-α, and IL-6 seem to be involved in the inflammatory phase of the infection." (PMID 33374214, 2020). "Unpublished studies by our laboratory indicated that IL-2 and IFN-γ production were the most readily quantified for influenza-specific CD4 T cells post vaccination." (PMID 32884842, 2020). "We were particularly interested in IL-2, IL-12p70, IFN-γ, IL-1β, IL-10, IL4, and TNF-α, given their involvement in the immune response during influenza infection and also given the phenotype of the response upon vaccination." (PMID 28792466, 2017). "During influenza infection, the binding of T-bet to cytotoxic gene promoters in CD4 T cells is regulated by Blimp-1 expression via a mechanism involving IL-2, type I interferons, and STAT2 signaling." (PMID 28167943, 2017). "In mice, CD4 effectors of multiple subsets including helper type 1 (Th1) cells producing interleukin-2 (IL-2) and IFNγ that recruit virus-specific cytotoxic T lymphocytes (CTL) to the lungs to kill influenza-infected lung epithelial cells." (PMID 26941738, 2016). "In this current study, we examined the effects of IL-2 and IL-6 on the CD8+ T cell response to influenza virus and showed that the addition of these cytokines restored the response to influenza in aged mice to that observed in young mice." (PMID 27322555, 2016). "In summary, these data indicate that CD4+ T cells are involved in the immune response to influenza infection in pigs and that a considerable proportion of responding cells is multifunctional in terms of IFN-γ, TNF-α and IL-2 production." (PMID 25971313, 2015). "We have previously evaluated the efficacy of membrane-anchored interleukins (IL) such as IL-2 and IL-4 co-presented as Cytokine-bearing Influenza Vaccines (CYT-IVACs) using a mouse model of influenza challenge." (PMID 24884849, 2014). "As with the IFN-γ response, the N3OASq group had the strongest IL-2 response against all three influenza stimuli, but the N3OA and the EndocineTM group also responded with significantly higher IL-2 release than the non adjuvanted group." (PMID 23950951, 2013). "Two months after influenza infection, rVV-NP challenge induced the accumulation of functional CD8+ T cells capable of ex vivo degranulation and/or expression of IFN-γ and/or IL-2." (PMID 22965681, 2012). "Multiparametric flow cytometry assays were performed to determine the relative importance of the subpopulations of influenza-specific CD3+CD4+ and CD3+CD8+ T cells that produce IL-2, IFN-γ, and TNF-α." (PMID 20520820, 2010). "Previous studies from our lab identified functional defects in antigen-specific peripheral T follicular helper cells (pTfh), characterized by low IL-21 and high IL-2 production, contributing to non-responsiveness to the influenza vaccine in both aging and HIV." (PMID 41801310, 2026). "Additionally, airway Tregs upregulated influenza infection, IFN-α/β signaling, and IFN-γ signaling pathways, but downregulated IL-2 production, TGF-β, TNF-α, Toll-like receptor (TLR), TCR, and MAPK signaling pathways in COPD." (PMID 40589761, 2025). "In any case, despite the putative adverse effects of IL-2, treatment with low-dose rIL-2 and IL-2/anti-IL-2 Ab complexes efficiently decreases anti-DNA Ab titers in NZB/W F1 mice and hinders influenza-specific B cell responses in influenza-infected mice." (PMID 33986755, 2021). "The anti-inflammatory activities of sesamin have been shown also, in influenza H1N1-induced peripheral blood mononuclear cells of humans by either the reduction in the expression levels of both IL1B and TNFA genes or the increase in the expression of IL2 gene." (PMID 33578642, 2021).
influenza (continued). "We also found that NK cells, but not T cells, expanded by IL-2 drive inflammatory responses that worsen the outcome of influenza infection in mice." (PMID 32728053, 2020). "There was limited induction of IL‐2 from CD4+ T cells, which could, in part explain the paucity of CD4+ T‐cell‐dependent NK‐cell responses on re‐stimulation with influenza antigen in vitro." (PMID 28383105, 2017). "Indeed, a significant increase in IL2 levels was observed in the culture supernatant of BW-NKp44 and BW-NKp46 cells following incubation with PR8 influenza 721.221 cells, indicating that both the BW-NKp44 and BW-NKp46 reporter systems function properly." (PMID 27029068, 2016). "IL-2 treatment has been shown in the mouse to restore the effector phase of the response to influenza in the absence of CD28 costimulation." (PMID 27322555, 2016). "Given the role of IL-2 and IL-2Rα in the generation of cytolytic effectors in vitro, we next wanted to determine the contribution of IL-2Rα (CD25) in the generation of CD4 CTL in vivo in response to acute influenza infection." (PMID 24586481, 2014). "The human CD4 T cell memory response to influenza is normally skewed strongly to the Th1 pattern of cytokine expression, including mainly cells secreting IFNγ, TNFα and IL-2 but not IL-4." (PMID 23526940, 2013). "Furthermore influenza-specific CD8+DbNP366+ and DbPA224+CD8+ T cells were stimulated in vitro with relevant peptide and cytokine expression (IFN-γ, TNF-α and IL-2) detected using intracellular cytokine staining." (PMID 21304882, 2011). "Because ATL cells typically have a Treg-like suppressor phenotype and since the absence of BLIMP1 resulted in enhanced IL-2 signaling in cTreg cells during influenza infection, we next investigated the role of BLIMP1 in IL-2 signaling in ex vivo–isolated Treg cells." (PMID 40680114, 2025). "In addition, IMP321 has been described to enhance the response of Th1 influenza-specific CD4+ cells by increasing the secretion of IFN-γ, the prototypical Th1 effector cytokine, TNF-α, an inflammatory cytokine, and IL-2, which is involved in the development of memory T cells." (PMID 36680187, 2023). "Thus, IL-2 has been one of the most extensively studied molecular adjuvants and has shown increased immunogenicity for previously low-immunogenic vaccines such as HIV, influenza, and SARS-CoV." (PMID 33937377, 2021). "However, some authors suggest that, unlike its effects on conventional Treg cells, IL-2 inhibits Tfr-like cell responses during influenza infection." (PMID 34350197, 2021). "Intra cellular cytokine staining revealed that the majority of CD8 influenza specific T cells in the BAL secreted IFNγ and TNF (39.9%), followed by IFNγ only producers (35.7%) and 14.5% produced all three cytokines (IFNγ, TNF, and IL-2), while CD4 T cells produced mainly IFNγ (49.3%)." (PMID 33193445, 2020). "Furthermore, supplementation with silk peptide in non-seasonal influenza vaccine subjects for 8 weeks increased levels of cytokines (IL-2, IL-12, and IFN-γ) and NK cell activity." (PMID 32498269, 2020). "We found that IL-2 production by Ag.pTfh had a negative impact on the influenza Ab response." (PMID 31100059, 2019). "Moreover, when the influenza coated cells were incubated with anti HA blocking antibody there a reduction in IL-2 secretion was detected and IL-2 levels were similar to those observed without influenza." (PMID 26919106, 2016). "Since this effect of IL-2/IL-6 supplementation can be reproduced with the addition of Toll-like receptor agonists, it may be possible to exploit this mechanism and design new vaccines to improve the CD8 T cell response to influenza vaccination in older adults." (PMID 27322555, 2016). "For example IL-2,a critical regulator of Treg viability and maintenance, could potentially help sustain Treg responses in the late phase of influenza infection, with CD4+ T effector cells serving as a source of IL-2 through a CD86 engagement dependent mechanism." (PMID 25144228, 2014).
influenza (continued). "Thus in human influenza-specific memory CD4 T cells, the IFNγ+ cells may variably express IL-2, but 2+γ- cells may include cells with a distinct differentiation state." (PMID 24788814, 2014). "The IL-2+ producing T cell bias was not due to overlap of the IL-2+ T cells with T follicular helper (Tfh) cells, as the majority of both IFNγ+TNFα+ and IFNγ−IL-2+TNFα+ influenza-specific cells responding to CA/09 and NC/99 were found within the CXCR5− CD4 T cell population." (PMID 23526940, 2013). "An alternative interpretation of our data is that control of some viruses requires differential functional profiles: a polyfunctional response led by IL-2 is necessary for EBV and influenza, while CMV and Adenovirus may need to be controlled or cleared by a perforin-dominated response." (PMID 20221423, 2010). "In contrast, responses to influenza in subjects belonging to this same cohort showed a more functional response with 10 out of 15 responders to an A2-restricted Flu peptide producing both IFN-γ and IL-2 or IL-2 alone while the remaining 5 produced only IFN-γ ELISPOT responses (data not shown)." (PMID 18846233, 2008). "In contrast, the expression of CD25 was lower on lung tissue resident Treg cells compared to their circulating and splenic counterparts suggesting that IL-2 signaling may not be the predominant signal for lung tissue resident Treg cell maintenance following influenza infection." (PMID 36159872, 2022). "However, not all influenza-specific CD4 T cells express both IL-2 and IFNγ." (PMID 24788814, 2014). "Moreover, a longitudinal study on response to influenza vaccine demonstrated a significant increase of antigen specific IFN-γ gene expression two weeks after immunization, declining thereafter, whereas increased IL-2 gene expression was still detectable four months after vaccination." (PMID 18925935, 2008). "In influenza infection, ICOS stimulation is needed to maintain FOXP3 expression in the absence of IL-2." (PMID 36672230, 2023). "This is in agreement with previous findings that after A(H1N1)pdm09 exposure, a primed IFN-γ-IL2+TNF-α+ non-polarized precursor T-cell population (Thpp) has been observed, representing a recently induced memory response to influenza." (PMID 26606759, 2015). "Vaccination also did not appear to affect the frequency of influenza-specific CD4+ or CD8+ T cells expressing Granzyme B and at least IFN-γ, and/or IL-2." (PMID 25078387, 2014). "Often, a defective cellular immunity leads to decreased memory B cell expansion and impaired antibody production, as occurs with H1N1/09 influenza vaccine non-responders where failure in CD4+ T cell stimulation and IL-2 secretion concurs with a low percentage of IgG antibody-secreting cells." (PMID 35860236, 2022). "In another study, higher frequency of preexisting IFN-γ+IL-2- CD8+ T cells specific to conserved core protein epitopes inversely correlated with symptom score, and correlated with crossprotection against influenza in the absence of crossreactive neutralizing antibodies." (PMID 24690681, 2014). "Additionally, SARS-CoV-2 can increase pro-inflammatory cytokines, including interleukin (IL)-2, IL-6, IL-7, and tumor necrosis factor-alpha (TNF-a), to levels not typically seen in bacterial sepsis or influenza and contribute to thrombosis formation via multiple mechanisms." (PMID 38903348, 2024). "Similarly, receipt of the TIV during the same influenza season did not impact the magnitude of the subsequent influenza-specific CD8+ T-cells response, with the exception of a stronger IL2+CD8+ T-cell response at influenza diagnosis among patients who received the TIV (p = 0.039)." (PMID 32572168, 2020).
colitis (151 papers, 2007 to 2025). Inflammation of the colon. "Consistent with this idea, a recent study reported that the duplication of IL2RA locus results in excessive IL-2 signaling and that this predisposed to colitis in patients with inflammatory bowel disease." (PMID 40680114, 2025). "In previous studies, IL-10 or IL-2 deficient mice spontaneously develop colitis in a gut bacteria-dependent manner." (PMID 38874761, 2024). "It was reported that IL-2 (IL-2−/−) and IL-2Rα-deficient (IL-2Rα−/−) mice develop spontaneous colitis and systemic wasting disease." (PMID 35055297, 2022). "In fact, a high rate of colitis, with striking clinical and morphological similarities to ulcerative colitis, was reported in a IL-2-deficient mouse model." (PMID 36432588, 2022). "For instance, mice deficient in the anti-inflammatory cytokines IL-2 or IL-10 develop spontaneous colitis." (PMID 33435303, 2021). "Th2 cells regulate the inflammatory response that causes colitis, and IL-2 is involved in the suppression of inflammatory process and severity reduction of colitis by influencing Th2 cells." (PMID 32849906, 2020). "The subsequent induction and expression of various inflammatory cytokines (TNF-α, IL-6, IL1β, IL-17, and IFN-γ) and enzymes (iNOS and COX-2) that are associated with the initiation and development of colitis 49, 79 were also prevented by low-dose IL-2." (PMID 32308767, 2020). "We demonstrated that treatment with low-dose IL-2 blocked the intestinal tissue damage otherwise caused by DSS-induced colitis in mice." (PMID 32308767, 2020). "Thereby, our and other groups used genetically susceptible colitis mouse models (Rag1-, IL-2-, and IL-10-deficient) exhibiting a dysregulated immune system to mimic disease development in an immune suppressed host." (PMID 32038631, 2019). "Vice versa, E. coli induces colitis in gnotobiotic IL-2-deficient mice, but co-association with B. vulgatus prevents colitis development." (PMID 31281321, 2019). "Moreover, in two murine colitis-associated carcinogenesis models (DSS-induced colitis and interleukin 2 knockout), tumor burden in response to dietary iron was observed to increase in comparison to parenteral iron administration." (PMID 36982582, 2023). "Some B. vulgatus strains attenuated intestinal inflammatory responses, for example, B. vulgatus mpk protected against Escherichia coli-induced colitis in interleukin-2-deficient mice by inducing a host anti-inflammatory immune response and B. vulgatus 7K1 had protective effect on mouse colitis." (PMID 36531989, 2022). "coli-induced colitis in IL-2−/− mice, while IL-10−/− mice mono-associated with pig isolates of B." (PMID 36376984, 2022). "Furthermore, B. vulgatus has been shown to be protective against Escherichia coli induced colitis of interleukin-2-deficient gnotobiotic mice." (PMID 35432282, 2022). "IL-2 is an effector cytokine produced by Th2 cells, which has been closely associated with colitis." (PMID 32849906, 2020). "A similar therapeutic function of OPG in gut-inflammation associated bone loss was also found in IL-2−/− colitis mice, in which both skeletal abnormalities and colitis score were reduced by modulation of RANKL-RANK interactions with exogenous administration of Fc-OPG." (PMID 31847438, 2019). "This work suggests activated T cells, due to IL-2 deficiency, may contribute to induction of bone loss in the setting of colitis by inducing OC formation." (PMID 31847438, 2019). "Furthermore, IL-10 knockout and IL-2-deficient mice manifest differential levels of severity of colitis dependent on the types of taxa that colonize their gut." (PMID 28904997, 2017). "Waidmann and his colleagues had described the isolated B. vulgates strain with possible probiotic propertites that was able to ameliorate E. coli induced colitis development by an yet unknown mechanism in interleukin-2-deficient mice." (PMID 24603888, 2014).